CLDND2 (claudin domain containing 2)
Synonyms: MGC33839
Tractability: Antibody: UniProt predicts a signal peptide or a membrane-spanning region; its Gene Ontology location is reachable by antibodies, with medium confidence.
Gene: Protein-coding gene on chromosome 19 (51,367,098 to 51,369,003, reverse strand). Ensembl gene ENSG00000160318.
Subcellular location: Membrane
Subcellular location (Human Protein Atlas): Nucleoplasm
Gene Ontology:
Molecular function: protein binding
Cellular component: plasma membrane; membrane
Genetic constraint (gnomAD): Loss-of-function variants: 18 observed, 16.82 expected, observed/expected ratio (o/e) 1.07, 90% interval 0.74 to 1.58. The upper end of that interval is the gene's LOEUF score, 1.58, which puts it in group 6 of 6, group 1 being the genes least tolerant of losing a copy. Missense variants: 233 observed, 223.73 expected, observed/expected ratio (o/e) 1.04, 90% interval 0.94 to 1.16. Synonymous variants: 113 observed, 90.14 expected, observed/expected ratio (o/e) 1.25, 90% interval 1.08 to 1.47.
Homologues: Orthologues: chimpanzee CLDND2 (99% identical), macaque CLDND2 (86% identical), pig CLDND2 (78% identical), dog CLDND2 (76% identical), rat Cldnd2 (72% identical), mouse Cldnd2 (70% identical). Paralogues in human: LIM2 (28% identical), GSG1L2 (21% identical), PMP22 (20% identical), TMEM202 (19% identical), GSG1L (18% identical), NKG7 (18% identical), EMP1 (17% identical), GSG1 (17% identical), EMP2 (16% identical), EMP3 (15% identical).